TLR7 (toll like receptor 7)
Diseases named in the same sentence as TLR7 in open-access papers (continued):
Sharing a sentence is not in itself a finding about the gene and the disease.
chronic asthma (2 papers, 2019 to 2025). An asthma that is characterized by the development of persistent airway inflammation and recurrent attacks of breathlessness and wheezing, which vary in severity and frequency. "Toll-like receptors (TLRs) play a key role within the innate immune system and TLR7 agonists have previously been shown to up-regulate Th1 responses and down-regulate Th2 responses to allergens in murine models of allergic or chronic asthma." (PMID 31856838, 2019).
Crohn disease (2 papers, 2012 to 2025). A gastrointestinal disorder characterized by chronic inflammation involving all layers of the intestinal wall, noncaseating granulomas affecting the intestinal wall and regional lymph nodes, and transmural fibrosis. "For example, TLR7, NFKBIA, NFKBIZ, NFKB2, and TNFRSF19 have been shown to be upregulated in epithelial cells and macrophages during infection with AIEC strains isolated from Crohn’s disease patients." (PMID 40572318, 2025).
emphysema (2 papers, 2023 to 2024). "TLR7-deficient (Tlr7−/−) mice are protected against CS-induced emphysema-like alveolar enlargement associated with attenuated airway remodeling, apoptosis and mast cell numbers in the lungs of a mouse model of experimental COPD." (PMID 37963864, 2023). "Research indicated that abundance increases the number of TLR7-deficient mice presenting with a decreased severity of COPD and emphysema in a CS exposure model." (PMID 39189263, 2024). "Our study provides new insights and possible mechanisms of how TLR7 potentiates tissue-specific responses through mast cells, and shows that prophylactic and therapeutic targeting of TLR7 reduced lung mast cell numbers, emphysema and experimental COPD." (PMID 37963864, 2023). "Precisely how TLR7 signaling and MyD88 activation regulate mast cell function to drive emphysema and COPD remain to be determined in future studies." (PMID 37963864, 2023). "CS-induced emphysema, apoptosis, airway remodeling, and mast cells are reduced in mice following therapeutic neutralization of TLR7." (PMID 37963864, 2023). "Next, we determined if imiquimod-induced emphysema has a short-term effect and is TLR7- and MyD88-dependent." (PMID 37963864, 2023). "This suggests that the effects of TLR7-induced emphysema are likely to involve soluble tryptases or mediators released from mast cells." (PMID 37963864, 2023). "Conversely, imiquimod stimulation of TLR7 induced emphysema and apoptosis in mouse lungs, which synergistically increased with CS exposure." (PMID 37963864, 2023). "In summary, we discover an unexpected role for TLR7 in mediating emphysema and COPD through mast cell-specific tryptase activity." (PMID 37963864, 2023). "Collectively, our study demonstrates a role for TLR7 in mast cells and provides new insights into the mechanisms of TLR7-driven emphysema and COPD." (PMID 37963864, 2023). "Tlr7−/− mice had reduced CS-induced emphysema and airway remodeling and improved lung function in experimental COPD." (PMID 37963864, 2023). "Additionally, mice treated with an anti-TLR7 monoclonal antibody present with a reduction in CS-induced emphysema and experimental COPD and display a reduction in the accumulation of pulmonary mast cells." (PMID 39189263, 2024). "In contrast, the inhalation of imiquimod, an agonist for TLR7, caused mice to present with emphysema, even in the absence of CS exposure." (PMID 39189263, 2024). "Thus, our study defines TLR7 as a promising treatment target and opens a new avenue for developing new therapies to reduce or reverse the severity of emphysema and COPD, as well as mast cell-related diseases." (PMID 37963864, 2023). "Furthermore, therapeutic treatment with anti-TLR7 monoclonal antibody suppresses CS-induced emphysema, experimental COPD and accumulation of pulmonary mast cells in mice." (PMID 37963864, 2023). "Here the authors show that TLR7 may also contribute, via the modulation of mast cell functions, to experimental, cigarette smoke-induced mouse models of emphysema, thereby hinting TLR7 as a potential therapeutic target for human lung inflammation." (PMID 37963864, 2023). "Thus, our study is to demonstrate unexpected roles for TLR7 in apoptosis in the lung, emphysema, and experimental COPD." (PMID 37963864, 2023). "We next determined that TLR7 has a role in CS-induced emphysema-like alveolar enlargement." (PMID 37963864, 2023). "Here we show that the severity of CS-induced emphysema and COPD is reduced in TLR7-deficient mice, while inhalation of imiquimod, a TLR7-agonist, induces emphysema without CS exposure." (PMID 37963864, 2023). "CS- and imiquimod-induced emphysema is TLR7- and MyD88-dependent." (PMID 37963864, 2023). "It remains unknown exactly why TLR7 increased and how TLR7, MyD88, and mMCP-6/hTrypase-β induce degranulation and emphysema and these mechanisms need to be defined." (PMID 37963864, 2023).
emphysema (continued). "We have also recently demonstrated the critical role of increased Toll-like receptor 7 (TLR7) responses in COPD, driving the destruction of alveolar epithelial cells that promote pulmonary emphysema." (PMID 39189263, 2024). "We have also recently demonstrated the critical role of increased TLR7 responses in COPD, which drive the destruction of alveolar epithelial cells that promote emphysema." (PMID 39189263, 2024). "We show that TLR7 is increased in human and experimental COPD, and promotes alveolar destruction, emphysema, and experimental COPD through mast cell tryptase activity." (PMID 37963864, 2023). "Our results thus support roles for TLR7 in mediating emphysema and COPD through mast cell activity, and may implicate TLR7 as a potential therapeutic target." (PMID 37963864, 2023). "Hence, TLR7 does not have a major role in CS-induced inflammation, and the effects on emphysema and COPD are inflammation-independent." (PMID 37963864, 2023). "However, the role of TLR7 in COPD/emphysema is unknown, and there are no known links between TLR7 and mast cell-specific mediators." (PMID 37963864, 2023).
enterovirus infection (2 papers, 2014 to 2019). "However, a number of studies have demonstrated that TLR7 and TLR8 can be induced upon enteroviral infection." (PMID 31117206, 2019). "Although the role of TLR7 and TLR8 have not been extensively studied during enterovirus infection, it is becoming clear that these PRRs may play key roles in the induction of proinflammatory cytokines." (PMID 31117206, 2019).
food allergy (2 papers, 2016 to 2021). Gastrointestinal disturbances, skin eruptions, or shock due to allergic reactions to allergens in food. "In this work, we have synthesized two family of ligands,an 8-oxoadenine derivative as a ligand for TLR7 and a pyrimido[5,4-b]indole as a ligand for TLR4, both conjugated with a T-cellpeptide of Pru p 3 allergen, the lipid transfer protein (LTP) responsiblefor LTP-dependent food allergy." (PMID 34761908, 2021).
Granuloma (2 papers, 2021 to 2022). A compact, organized collection of mature mononuclear phagocytes, which may be but is not necessarily accompanied by accessory features such as necrosis. "Moreover, TLR7 deficiency aggravates S. japonicum infection-induced damage in the lung, with more inflammatory cells infiltration, interstitial dilatation and granuloma in the tissue." (PMID 36279265, 2022). "Finally, we found TLR7 deficiency aggravates S. japonicum infection-induced damage in the lung, with more interstitial dilatation, thickened alveolar cavity and granuloma." (PMID 36279265, 2022). "A large number of granulomas surrounding the egg were observed in the liver tissue of infected WT mice, but few granulomas were found in infected TLR7 KO liver tissue, in which there were many nude eggs, indicating poor granuloma reaction in TLR7 KO mice." (PMID 34692568, 2021). "It is hypothesized that the death of TLR7 KO mice in the early phase of S. japonicum infection may be related to the absence of granulomas around the eggs." (PMID 34692568, 2021).
histoplasmosis (2 papers, 2016 to 2020). A disease caused by the fungus Histoplasma capsulatum. "In the histoplasmosis model, TLR7/TLR9-deficient animals show a more aggressive infection, exhibiting increased neutrophil recruitment, increased lung damage, colonization in the brain, and consequently increased death." (PMID 33194839, 2020). "Since brain colonization has not been extensively characterized in the mouse model of histoplasmosis, we infected TLR7/9-/- mice with mCherry-producing Histoplasma and performed flow cytometry analysis on brain homogenates at the time of peak colonization (14 dpi)." (PMID 27459510, 2016).
human papilloma virus infection (2 papers, 2023). An infectious process caused by a human papillomavirus. "Imiquimod, a TLR7 agonist, is utilized for curing genital and perianal warts caused by human papilloma virus infection." (PMID 38003793, 2023).
Hyperglycemia (2 papers, 2024 to 2025). An increased concentration of glucose in the blood. "Thus, it is possible that Tlr7-deficient NOD/ShiLtJ male animals had reduced hyperglycemia as compared Tlr7-sufficient controls, and this may have also indirectly diminished the inflammation within the lacrimal tissue." (PMID 39310226, 2024). "Limitations of the study and future perspective: The study highlights the effects of hyperglycemia on the expression of CD36, CD69, CD274, and TLR-7 in rat tissues and rat fibroblasts." (PMID 41465460, 2025). "There was no significant change in the protein expression of TLR-7 protein expression with hyperglycemia." (PMID 41465460, 2025). "Hyperglycemia also modulated the expression of CD274 and TLR-7." (PMID 41465460, 2025). "Immunofluorescence studies also suggest that hyperglycemia does not have a significant effect on TLR-7 expression in fibroblasts." (PMID 41465460, 2025). "This study aims to investigate the effects of hyperglycemia on the expression of various factors, including surface receptors CD36, Toll-like receptor (TLR)-7, programmed death-ligand 1 (PD-L1, also known as CD274), and CD69, in tissues from diabetic rats compared to control rats." (PMID 41465460, 2025). "However, the effects of hyperglycemia on the expression of mediators of inflammation and angiogenesis (CD36), immune regulation (TLR-7 and CD69), and inflammation/tissue repair (CD274) regarding wound healing are unknown." (PMID 41465460, 2025). "Hyperglycemia significantly increases the expression of CD36, CD69, and CD274 and increases TLR-7 expression but not significantly in diabetic tissues compared to control tissues." (PMID 41465460, 2025).
Hyperinsulinemia (2 papers, 2022 to 2024). An increased concentration of insulin in the blood. "Together with our data, these studies show potential for the involvement of TLR7 signaling in the development of dysglycemia and hyperinsulinemia, although the mechanisms underlying these effects remain to be further elucidated." (PMID 35874527, 2022). "We previously demonstrated hyperinsulinemia in TLR7 agonist imiquimod (IMQ)‐treated, high‐fat diet (HFD)‐fed female C57BL/6 mice." (PMID 38346802, 2024).
Hyperkeratosis (2 papers, 2022 to 2023). Hyperkeratosis is a histopathological term defining a thickened stratum corneum and may be present in many different skin conditions, with many possible overlaps. "We observed a significant increase in inflammatory factors (such as TNF-α, IL-1β, CXCL1, CXCL2, CCL4, and TLR7) and exacerbates hyperkeratosis and keratosis in STAT3 mice." (PMID 37465147, 2023).
IgA nephropathy (2 papers, 2022 to 2023). "In a clinical trial on patients with IgA nephropathy, the investigators found that toll-like receptor 7 (TLR7) can activate B cells through the TLR7- GALNT2 axis, which produces high levels of galactose-deficient IgA1 (Gd-IgA1)." (PMID 35251009, 2022).
inflammatory skin disorder (2 papers, 2013 to 2024). "One example is AOP ID 313 ‘Stimulation of TLR7/8 in dendritic cells leading to Psoriatic skin disease’, an inflammatory skin disorder categorized under ‘Diseases of the skin’." (PMID 38523647, 2024). "Regulation of TLR7 in keratinocytes could be potential therapeutic strategies for treating skin inflammatory diseases." (PMID 24146965, 2013). "However, our results indicate that TLR7 in keratinocytes could play an important role in the pathogenesis of skin inflammatory diseases." (PMID 24146965, 2013). "Our data provide compelling evidence that imiquimod stimulates NF-κB, IL-8 and TNF-α expression in keratinocytes via TLR7, and it is tempting to propose that modulation of these pathways could be an interesting candidate for the treatment of inflammatory skin diseases." (PMID 24146965, 2013).
Insulin resistance (2 papers, 2022 to 2024). Increased resistance towards insulin, that is, diminished effectiveness of insulin in reducing blood glucose levels. "The current study, as well as recent work by our group and others suggest that enhanced TLR7 activation may exacerbate the development of MetS features, including impaired glucose homeostasis and insulin resistance." (PMID 38346802, 2024).
interstitial nephritis (2 papers, 2024 to 2025). Inflammation of the renal tubules and supporting tissues of the kidney. "Interstitial nephritis was significantly decreased in male Tlr7 and Cybb double-KO mice." (PMID 39042716, 2024).
lung squamous cell carcinoma (2 papers, 2021 to 2023). "TLR7 is also expressed in adenocarcinoma and squamous-cell carcinoma of the lung and promotes cancer cell survival through NF-κB activation and upregulation of Bcl-2." (PMID 34573939, 2021).
macrophage activating syndrome (2 papers, 2019 to 2025). "Chronic signaling through TLR7 and TLR9 is also associated with driving the differentiation of inflammatory hemophagocytic cells, leading to anemia and thrombocytopenia observed in conditions such as macrophage activation syndrome (MAS) and malaria." (PMID 40510367, 2025). "Thus, early mortality was most likely the result of TLR7-induced myeloproliferative disease, likely a histiocytic proliferative syndrome or a histiocytic sarcoma, although given the observed hemophagocytosis and high mortality, a macrophage activating syndrome like disease cannot be ruled out." (PMID 31998321, 2019).
malignant mesothelioma (2 papers, 2014 to 2015). A malignant neoplasm of the pleura or peritoneum, arising from mesothelial cells. "Regarding the administration method, it was reported that the local administration of the TLR7 agonist imiquimod with anti-CD40 immunotherapy exhibited a strong antitumour effect in a murine model of malignant mesothelioma." (PMID 25887995, 2015). "We therefore tested the efficacy of the TLR7 agonist imiquimod (IMQ) combined with agonistic anti-CD40 in an incomplete debulking model of malignant mesothelioma." (PMID 25518732, 2014).
metabolic dysfunction-associated steatohepatitis (2 papers, 2022 to 2025). Metabolic dysfunction-associated steatohepatitis (MASH, formerly known as nonalcoholic steatohepatitis or NASH) is a type of fatty liver disease. "TLR7 was among several differentially-upregulated genes identified in the livers of a nonalcoholic steatohepatitis model in minipigs that was induced by chronic feeding of a high-fat, high-sucrose diet." (PMID 35874527, 2022).
myocardial ischemia (2 papers, 2018 to 2022). A disorder of cardiac function caused by insufficient blood flow to the muscle tissue of the heart. "However, the role of TLR7 in myocardial ischemia and IRI may be less significant than TLR9 given that IS in TLR9−/− mice did not change with administration of HCQ." (PMID 36081846, 2022).
nasopharyngeal carcinoma (2 papers, 2022 to 2024). A carcinoma arising from the nasopharyngeal epithelium. "However, there are limited data on the association between TLR7 and TLR9 polymorphisms and prognosis or susceptibility to oral cancer or other subtypes of HNSCC, such as nasopharyngeal carcinoma (NPC)." (PMID 38850110, 2024). "A retrospective study on 150 Finnish nasopharyngeal carcinoma (NPC) tumor samples by immunohistochemistry showed that TLR7s were highly expressed in NPC and patients with positive TLR7 tumor expression had better OS than those with no TLR7 expression." (PMID 36476317, 2022).
neuromyelitis optica (2 papers, 2024). A rare inflammatory disease of the central nervous system characterized mainly by attacks of uni- or bilateral optic neuritis (ON) and acute myelitis. "Further, gain-of-function (GOF) mutations in human TLR7 were recently identified to cause severe autoimmune phenotypes, specifically, SLE and neuromyelitis optica." (PMID 38324161, 2024).
non-melanoma skin carcinoma (2 papers, 2022 to 2024). "TLR7, which recognizes single-stranded RNA (ssRNA), was also investigated using imiquimod, a TLR7 agonist used clinically to treat non-melanoma skin cancers (NMSCs)." (PMID 39348939, 2024).
oral cancer (2 papers, 2023 to 2024). "TLR9 and TLR7 polymorphisms could potentially have a role in the modulation of immune responses to alcohol-associated DAMPs, and the impaired initiation of anti-tumor immune response in oral cancer." (PMID 38850110, 2024). "Polymorphisms in TLR7 and TLR5 were recently associated with oral cancer suppression, while polymorphisms in TLR4 and TLR2 were associated with oral cancer progression." (PMID 38850110, 2024). "Since oral cancer is closely associated with HPV infection, TLR7 and TLR9 as endogenous sensors of viral nucleic acids may play a significant role in the malignant transformation in OSCC." (PMID 38850110, 2024).
osteosarcoma (2 papers, 2020 to 2025). A usually aggressive malignant bone-forming mesenchymal neoplasm, predominantly affecting adolescents and young adults. "As expected, silencing TLR7 led to a decrease in the migratory and invasive capabilities of osteosarcoma cell lines, suggesting it as a potential target for metastasis treatment." (PMID 40079158, 2025). "For instance, toll‐like Receptor 7 (TLR7) was identified as a DEG in osteosarcoma samples using RNA‐Seq." (PMID 40079158, 2025).
pancreatitis (2 papers, 2021 to 2024). Inflammation of the pancreas. "In the present study, upregulation of TLR7, IRF7, and IFN-β expression was observed in the pancreatitis-associated DHAV-1 and classical-type DHAV-1 groups, which is consistent with the findings of previous studies." (PMID 34482448, 2021). "As shown in this study, the initial event causing pancreatitis in the MRL/MpJ model is most likely IFN-α/β production by pancreatic tissue–resident TLR3-bearing cDCs stimulated by a disease-inducing TLR3 ligand such as poly(I:C), rather than IFN-α/β production by stimulated TLR7/9-bearing pDCs." (PMID 39264798, 2024).
periodontitis (2 papers, 2019 to 2022). An acute or chronic inflammatory process that affects the tissues that surround and support the teeth. "Moreover, one study reported in male participants that the reduced susceptibility to periodontitis was observed in carriers of TLR7-rs3853839-CC28." (PMID 35508687, 2022). "It has been shown that the cellular expression of all TLRs (apart from TLR7 and TLR8) differs significantly between healthy controls and periodontitis patients, implying a contribution in periodontitis’ pathogenesis." (PMID 31817424, 2019).
peritonitis (2 papers, 2012 to 2016). Inflammation of the peritoneum (tissue that lines the abdominal wall and covers most of the organs in the abdomen). "Therefore, we formulated 4C-Staph with a novel small molecule targeting TLR7 adsorbed to alum to give 4C-Staph/T7-alum, and tested this vaccine formulation as single dose in S. aureus kidney abscess and peritonitis mouse models." (PMID 26812180, 2016). "Hence it is possible that intervention with a weak TLR7 agonist could prove beneficial in other TLR-dependent models of peritonitis." (PMID 22619481, 2012).